ZNF483 (zinc finger protein 483)
Description:
May be involved in transcriptional regulation.
Synonyms: KIAA1962; ZKSCAN16; ZSCAN48
Tractability: PROTAC: ubiquitination databases record sites on it.
Gene: Protein-coding gene on chromosome 9 (111,525,054 to 111,577,844, forward strand). Ensembl gene ENSG00000173258.
Subcellular location: Nucleus
Subcellular location (Human Protein Atlas): Nucleoli
Pathways (Reactome):
Gene expression (Transcription): Generic Transcription Pathway
Gene Ontology:
Molecular function: DNA-binding transcription factor activity, RNA polymerase II-specific; RNA polymerase II cis-regulatory region sequence-specific DNA binding; sequence-specific DNA binding
Biological process: regulation of transcription by RNA polymerase II; regulation of DNA-templated transcription
Cellular component: nucleus
Genetic constraint (gnomAD): Loss-of-function variants: 7 observed, 25.54 expected, observed/expected ratio (o/e) 0.27, 90% interval 0.16 to 0.51. The upper end of that interval is the gene's LOEUF score, 0.51, which puts it in group 2 of 6, group 1 being the genes least tolerant of losing a copy. Missense variants: 636 observed, 880.37 expected, observed/expected ratio (o/e) 0.72, 90% interval 0.68 to 0.77. Synonymous variants: 309 observed, 311.8 expected, observed/expected ratio (o/e) 0.99, 90% interval 0.9 to 1.09.
Homologues: Orthologues: macaque ZNF483 (97% identical), chimpanzee ZNF483 (96% identical), dog ZNF483 (81% identical), pig ZNF483 (79% identical), guinea pig ZNF483 (60% identical), mouse Zkscan16 (57% identical), rat Zkscan16 (56% identical). Paralogues in human: ZNF606 (33% identical), ZNF33B (32% identical), ZNF41 (31% identical), ZNF484 (31% identical), ZNF658 (31% identical), ZNF334 (31% identical), ZNF879 (31% identical), ZNF568 (31% identical), ZNF615 (31% identical), ZNF30 (31% identical), ZNF7 (31% identical), ZNF717 (31% identical), and 164 more.
Diseases named in the same sentence as ZNF483 in open-access papers:
ZNF483 is named in the same sentence as 6 diseases in open-access papers, as found by Europe PMC text mining. Sharing a sentence is not in itself a finding about the gene and the disease. The quoted sentences say what the papers report.
acute lymphoblastic leukemia (1 paper, 2023). Leukemia with an acute onset, characterized by the presence of lymphoblasts in the bone marrow and the peripheral blood. "Interestingly, the loss of AKAP12 and ZNF483 expression were described in prostate cancer and acute lymphoblastic leukemia, respectively; on the other hand, AFTPH was the most up regulated circRNA in our analysis." (PMID 37106694, 2023).
lung squamous cell carcinoma (1 paper, 2024). "For lung squamous cell carcinoma, 9 genes were causally related, comprising U91328.19, FLOT1, LINC00243, HLA-DQA1, HLA-DQB1, HLA-DQB1-AS1, HLA-DQB2, ZNF483 and BLOC1S2." (PMID 38834983, 2024).
cancer (2 papers, 2023). A tumor composed of atypical neoplastic, often pleomorphic cells that invade other tissues. "The CIBAR1, CLIC4, OGN, and ZNF483 are protein-coding genes, but nothing is known about their association with PCa and cancer in general." (PMID 37298233, 2023). "Among these, AKAP12 and ZNF483 emerged as the most differentially down-regulated coding circRNAs whereas AFTPH, CHST15 and WDR37 were differentially up-regulated in the pan-cancer RNA-Seq dataset." (PMID 37106694, 2023). "In particular, ZNF483 and AKAP12 emerged as the strongest down-regulated circRNAs in cancer." (PMID 37106694, 2023).
ZNF483 also shares sentences with these, for which no sentence is quoted: glioma (1 paper); prostate carcinoma (1); tumor (1).